NLRP3 (NLR family pyrin domain containing 3)
Diseases named in the same sentence as NLRP3 in open-access papers (continued):
Sharing a sentence is not in itself a finding about the gene and the disease.
depression (continued). "The HMGB1/NF‐κB/NLRP3 signaling pathway is involved in DACA's therapeutic effects on depression." (PMID 40406924, 2025). "Furthermore, direct suppression of NLRP3 inflammasome activation by various inhibitors has been proposed as a promising therapeutic strategy for depression." (PMID 40573262, 2025). "However, its role in NLRP3 inflammasome regulation and synaptic plasticity during LPS-induced depression remains unexplored." (PMID 40427467, 2025). "Thus, a novel VTX molecular mechanism in modulating the NLRP3 inflammasome in a time- and area-specific manner in the brain was highlighted, with significant clinical implications in treating depression and cognitive impairments." (PMID 39005130, 2025). "Ruminococcus has the potential to impact lipids, including phosphoethanolamine and glycerophosphorylcholine as well as inflammatory signaling pathways, including the NLRP3 inflammasome, which may contribute to the etiology of depression." (PMID 39113894, 2024). "Enhanced oxidative stress after PM2.5 exposure can activate astrocytes via the Nrf2 pathway, as Nrf knockout mice exposed to PM demonstrate significantly upregulated pro-inflammatory cytokine expression and NLRP3 inflammasome activities, which has previously been reported to worsen depression." (PMID 39337247, 2024). "TaVNS can alleviate depression‐like behaviors induced by a high‐fat diet in ZDF rats which might be due to anti‐inflammation by up‐regulation of the P2X7R/NLRP3/IL‐1β signaling pathway in PFC." (PMID 38752512, 2024). "Therefore, the effect of P2X7R on NLRP3 inflammasome activation was investigated in atria under depression." (PMID 38261756, 2024). "Moreover, evidence indicates that ROS act as a key activator of the NLRP3 inflammasome, and a connection between depression and pyroptosis mediated by the NLRP3 inflammasome was reported recently." (PMID 39263574, 2024). "It is also suggested that NLRP3 plays a role in the pathogenesis of depression." (PMID 39443283, 2024). "It appears that increased production of IL‐1β and NLRP3 in the hippocampus may be effective in the development of increased depression‐like behaviors after ovariectomy." (PMID 39443283, 2024). "Moreover, MCC950, an inhibitor of the NLRP3 inflammasome, has been shown to ameliorate depression‐like behavior in mice by suppressing the activation of NLRP3 inflammasome in the hippocampus and reducing the expression levels of NLRP3, ASC, and IL‐1β." (PMID 38970230, 2024). "Furthermore, mangiferin downregulates the contents of IL-18, IL-1β, IL-6, and TNF-α in the hippocampus of the CUMS-induced depression mouse model by inhibiting the NLRP3/ASC/caspase-1 pathway." (PMID 38915473, 2024). "NLRP3 is a potential therapeutic target in a mouse model of chronic mild stress‐induced depression, and it may be a central mediator in the treatment of lipopolysaccharide (LPS)‐induced depression." (PMID 39443283, 2024). "Interestingly, NLRP3 inflammasome-mediated neuroinflammation is also a key factor that is relevant to depression." (PMID 38720779, 2024). "Consequently, interventions aimed at mitigating oxidative stress, ROS generation, NLRP3 inflammasome activity and pyroptosis are emerging as crucial targets for depression therapy." (PMID 39263574, 2024). "The NLRP3 inflammasome is involved in the pathogenesis of depression and may serve as a novel therapeutic strategy." (PMID 39684254, 2024). "Furthermore, depression-like behaviors can be alleviated by inhibiting the NLRP3 gene or with antidepressant treatment." (PMID 39337263, 2024). "Additionally, chronic swimming exercise (30 min per day, 5 times per week) and voluntary wheel exercise (averaging 8–12 km per night) also inhibited the NLRP3 inflammasome overactivation due to depression, high-fat diet, and chronic kidney disease." (PMID 39834360, 2024). "EA downregulated the expression of P2X7R/NLRP3/IL-1β and relieved depression-like behavior." (PMID 39367470, 2024).
depression (continued). "Depression can result in elevated levels of C-reactive protein, interleukin (IL)-1β, IL-6, and tissue necrotic factor-alpha, as well as an increase in the concentration of inflammatory molecules, such as NLRP3 inflammasomes." (PMID 39006364, 2024). "We, therefore, hypothesize that MT alleviates chronic stress-induced hippocampal microglia pyroptosis and subsequent depression-like behaviors by inhibiting the Cathepsin B/NLRP3 signaling pathway." (PMID 38538614, 2024). "Furthermore, the hippocampal downregulation of NLRP3 expression exhibited a mitigating effect on the depression-like behavioral manifestations and neuronal damage induced by CEE." (PMID 38983862, 2024). "Studies have found that NLRP3 activation is essential to depression and fatigue pathogenesis, and NLRP3/caspase-1 inhibition therapy may be a promising option for treatment." (PMID 39339809, 2024). "Interestingly, we found that the therapeutic effect of paeoniflorin was changed by blocking the expression of SIRT1, which indicated that SIRT1 and NLRP3/GSDMD played a key role in the relief of depression by paeoniflorin." (PMID 39684254, 2024). "Recent studies showed that NLRP3 inflammasome interacts with autophagy in depression." (PMID 38178196, 2024). "For instance, one study indicated that XYS might inhibit neuroinflammation to treat depression by regulating the TRIM31/NLRP3 inflammasome." (PMID 39185306, 2024). "In addition, the activation of the NLRP3 inflammasome has been detected in both individuals and animal models suffering from depression." (PMID 38916735, 2024). "Importantly, it has been indicated that fish oil enriched with n-3 PUFAs mitigated postpartum depression by inhibiting the NLRP3 inflammasome-driven inflammatory pathway in an animal model." (PMID 39203778, 2024). "Therefore, MT can alleviate hippocampal pyroptosis by inhibiting Cathepsin B/NLRP3 signaling pathway, thereby improving the depression-like behaviors of chronic stress rats." (PMID 38538614, 2024). "Hence, we propose that NLRP3 inflammasome‐induced microglial pyroptosis in the hippocampus is a significant contributor to depression‐like behavior." (PMID 38970230, 2024). "Pre-clinical studies show that the NLRP3 may be involved in depression by regulating the level of IL-1βin the serum and hippocampus." (PMID 38627683, 2024). "In the mice model of depression, miR-27a ameliorated NLRP3-mediated pyroptosis via SYK/NF-κB axis." (PMID 38421496, 2024). "Fourth, we did not re-evaluate the patients at another time point to investigate whether the presence of depression or the higher baseline NLRP3 levels predicted worse clinical outcomes." (PMID 37763063, 2023). "NLRP3 inflammasomes are considered important mediators of depression." (PMID 36979246, 2023). "The beneficial effect of luteolin through Sirt1/NF-κB/NLRP3 signaling pathway might be a therapeutic strategy for the depression-related dry eye disorder." (PMID 36641776, 2023). "Thus, we determined the causal relationship between local neuroinflammation and CPSP-related anxiety and depression by inhibiting thalamic HIF-1α/NLRP3 inflammatory signaling." (PMID 36944982, 2023). "The NLRP3-mediated inflammasome is regulated by miRNA-27a, a key factor in depression development." (PMID 38249586, 2023). "Taken together, we hypothesized that anxiety and depression in AR are associated with the presence of microglia-mediated inflammation in the ACC, which is partly due to dysregulation of the TET2/NLRP3 axis in microglia." (PMID 38012545, 2023). "NLRP3 inflammasome is the most highly expressed member in microglia, and the excessive activation of the NLRP3 inflammasome is involved in the pathogenesis of many brain disorders, including trauma, ischemia and major depressive disorder, as well as PD." (PMID 36829840, 2023). "The NLRP3 inflammasome may therefore constitute a new therapeutic target for the treatment of depression." (PMID 36909194, 2023).
depression (continued). "Therefore, improving the composition of microbiota via probiotic can attenuate inflammation by amending the microbiota and suppressing the activation of NLRP3 inflammasome, which is considered as a novel therapeutic strategy for depression." (PMID 37293210, 2023). "In addition to increased mRNA levels of HMGB1 in hippocampal microglia, higher expression of RAGE and activation of NLRP3 inflammasomes were found in the CUMS model of depression." (PMID 37296642, 2023). "Therefore, TET2 affects the activation of NLRP3/IL-1β pathway in microglia, which plays an important role in the occurrence and development of AR anxiety and depression-like behavior." (PMID 38012545, 2023). "NLRP3 was found to be overexpressed as a hub gene in the PFC of CORT-induced depression mice, suggesting that NLRP3 might play a key role and take part in the development and pathogenesis of depression." (PMID 36859349, 2023). "NLRP3 inflammasome activation is the pathogenesis of both chronic liver disease and depression." (PMID 36979246, 2023). "Numerous studies show that the NLRP3 inflammasome is essential for the development of depression." (PMID 36909194, 2023). "However, the likelihood of depression increased with increasing NLRP3 levels in myocardial infarction patients." (PMID 37763063, 2023). "Furthermore, the activation of NLRP3 inflammasome in prefrontal cortex in depression rats can be suppressed by fluoxetine, which is a widely used antidepressant." (PMID 37293210, 2023). "However, these abnormal indicators were gradually reversed after antidepressant administration, suggesting a close link between depression and the NLRP3 inflammasome." (PMID 37881439, 2023). "This study shows that inflammation factors such as ROS and NLRP3 are significantly upregulated in the hippocampal tissue of depressive mice, indicating that they play an important role in the occurrence and development of depression." (PMID 37629568, 2023). "To confirm the involvement of HIF-1α and NLRP3 in CPSP and associated anxiety and depression, we knocked down thalamic HIF-1α and NLRP3 through microinjection of HIF-1α siRNA or NLRP3 siRNA into the VPL of thalamus 3 days before microinjection of collagenase into the same regions." (PMID 36944982, 2023). "Our previous studies have found that chronic unpredictable mild stress (CUMS) stimuli induced depression-like behaviors, increased levels of IL-1β and IL-18 and altered the microbiota, which suggested NLRP3 inflammasome might be activated." (PMID 37293210, 2023). "There is a growing body of evidence reporting that targeting NLRP3-mediated inflammation in astrocytes may provide potential therapeutic benefits for the pathogenesis of depression." (PMID 37434240, 2023). "Our results found that CUMS treatment increased the expression of NLRP3 inflammasome and inflammatory cytokines in colon, which further indicated that depression and IBD might co-occur." (PMID 37293210, 2023). "The report suggested that the NLRP3 inflammasome may be a key mediator of stress-induced depression and a potential novel target for depression as a result of the NLRP3 inflammasome’s role in lipopolysaccharide (LPS)-induced depression." (PMID 36909194, 2023). "However, effect and mechanism of NLRP3 inflammasome on cognitive decline in depression remain to be elucidated." (PMID 37165444, 2023). "To achieve this, we firstly observed the prevention effects of H2S donor NaHS on LPS-induced depression-like behavior and inflammation in the hippocampus of mice, and then examined mitochondrial function and NLRP3 inflammasome activation in the hippocampus in response to LPS and NaHS pretreatment." (PMID 37626978, 2023). "However, in the logistic regression analysis, the NLRP3 variable in myocardial infarction patients was found to have a significant contribution to the likelihood of depression (p = 0.015, OR = 1.72, and CI = 1.11–2.66)." (PMID 37763063, 2023).
depression (continued). "Herein, we investigated whether berberine attenuate depressive-like behaviors via inhibiting NLRP3 inflammasome activation in mice model of depression." (PMID 36859349, 2023). "Thus, the study aimed to explore how NLRP3 inflammasome modulates cognitive decline in depression induced by chronic stress." (PMID 37165444, 2023). "On the other hand, NLRP3 inflammasome also can affect the abundance of microbiota to influence some disease, for example pancreatitis, colitis, depression-like behaviors." (PMID 37293210, 2023). "Findings from previous preclinical and clinical studies have indicated that NLRP3 inflammasome-driven pathways might be involved in numerous neuropsychiatric disorders including neuroinflammation-induced depression." (PMID 36859349, 2023). "NLRP3 inflammasome may affect the cognitive function of depression patients through these mechanisms." (PMID 37165444, 2023). "It has also been shown that the blockage of NLRP3 inflammasome activation by specific NLRP3 inflammasome inhibitors could alleviate depression-like behavior in mice." (PMID 37626978, 2023). "In this study, we aimed to investigate the possible role of the NLRP3 inflammasome and hsCRP in this comorbidity and to evaluate the relationship of these biomarkers with the presence and severity of comorbid depression in patients with acute myocardial infarction." (PMID 37763063, 2023). "Alleviate depression by inhibiting the NLRP3 inflammasome and kynurenine pathway." (PMID 37191432, 2023). "Similarly, fluoxetine, an FDA-approved drug for treating clinical depression, has recently been identified as a direct NLRP3 inhibitor that prevents the NLRP3-ASC assembly." (PMID 35883561, 2022). "It was hypothesized that the increased NLRP3 signaling due to stress/depression can lead to an overrepresentation of pro-inflammatory bacterial clades within the gut microbiota." (PMID 35546876, 2022). "This suggests that the increase in the protein expression of NLRP3, caspase-1, and IL-1β may have participated in anxiety-like and depression-like behavioral phenotypes in mice with atopic dermatitis." (PMID 36267291, 2022). "Based on these findings, calpains may act as intermediaries between reactive oxygen species (ROS) and NLRP3-dependent inflammation and may contribute to pathogenesis of depression." (PMID 35498131, 2022). "Although oxidative stress, neuroinflammation, and activation of NLRP3 are associated with the development of depression, the relationship among these factors has not been characterized." (PMID 35498131, 2022). "However, Rb1 exposure considerably reduced the NLRP3-mediated inflammatory response and restored depression-like behavioral responses in CSDS animals." (PMID 35634375, 2022). "Activation of NLRP3 has also been observed in patients with major depression." (PMID 35498131, 2022). "Therefore, the purpose of this study was to investigate the role of DHC on microglia activation and astrocyte A1/A2 phenotype in depression and the role of NLRP3 inflammasome in these effects." (PMID 36506556, 2022). "It is reported that depression can be improved by inhibiting NLRP3." (PMID 36267291, 2022). "Collectively, this study elucidated a novel mechanism in the pathogenesis of depression, and the results showed that the occurrence of oxidative stress and the activation of the NLRP3 inflammasome pathway were potentially mediated by excessive synthesis of xanthine, which in turn induced depression." (PMID 35847012, 2022). "Autophagy may interact with NLRP3 activation to contribute to the development of depression, whereas Sal B can promote autophagy and induce the clearance of NLRP3, thereby resulting in neuro-protective and antidepressant actions." (PMID 35991894, 2022). "It is suggested that muscone may alleviate IL-1β-related CNS inflammation through TLR4/MyD88 and TLR4/NLRP3 pathways, thereby attenuating LPS-induced depression-like behaviors." (PMID 35923544, 2022).
depression (continued). "Therefore, in this study, we observed the changes of NLRP3 and its downstream inflammatory cytokines of the two depression subtypes of patients." (PMID 35295780, 2022). "In addition, IL-1β secretion was closely controlled by the NLRP3 inflammasome, which plays an important role in the pathogenesis of depression." (PMID 35668399, 2022). "Clinical data regarding the involvement of NLRP3 in patients with depression are scarce." (PMID 35295780, 2022). "Similarly, the anti-inflammatory effect of ketamine has also been observed in a chronic restraint stress model of depression, inducing a reduction in the expression of NLRP3 inflammasome-related proteins in this model." (PMID 36613574, 2022). "In a clinical study, serum NLRP3 levels were increased in patients with major depressive disorder." (PMID 35498131, 2022). "Our study suggests that betaine may promote the transition of microglia from the M1 to the M2 phenotype by inhibiting NLRP3 inflammasome activation, thereby attenuating lipopolysaccharide-induced depression-like behavior." (PMID 36339940, 2022). "Moreover, the anti-inflammatory effect of chronic fluoxetine treatment was shown to be related to NLRP3 inflammasome modulation in the prefrontal cortex in a rat model of depression." (PMID 36613574, 2022). "In addition, BHB induction attenuated expression of IL-18, IL-1β and NLRP3 inflammasome in a rodent model of depression." (PMID 36533180, 2022). "Interestingly, we observed the characteristic hallmarks of pyroptosis in depression, which included increased activation of NLRP3 inflammasome and the release of IL-1β and IL-18." (PMID 35496273, 2022). "Previous studies have found that safflower extract could improve depression in mice by inhibiting TLR4/NLRP3 inflammatory signaling pathway." (PMID 36301036, 2022). "The NLRP3 inflammasome has been shown to be activated in patients with depression." (PMID 36339940, 2022). "Recent studies consider that inhibition of NLRP3 inflammasome activation may be a promising strategy for the therapy of depression." (PMID 35069768, 2022). "The increase in pro-inflammatory factors was positively correlated with Beck Depression Inventory scores, suggesting that NLRP3 might have a critical role in mediating the development of depression." (PMID 35668399, 2022). "Also, in an acute stress model, it was suggested that the improvement of depression-related symptoms by clomipramine treatment has something to do with NLRP3 inflammasome." (PMID 35688836, 2022). "Furthermore, the specific inflammasome inhibitor VX-765 blocked NLRP3 activation in the hippocampus and improved depression-like behavior in chronically unpredictable stressed mice." (PMID 35677442, 2022). "This suggests that NLRP3, caspase-1, and IL-1β may be involved in the anxiety-like and depression-like behavioral phenotypes of AD mice." (PMID 36267291, 2022). "Mounting evidence has suggested that the TLR4/NLRP3 signaling pathways may be the new targets for the development and treatments for depression." (PMID 35295780, 2022). "Additionally, isoliquiritin and kanglexin improve depression by downregulating NLRP3 levels and subsequent neuronal pyroptosis." (PMID 35937897, 2022). "In addition, there was significant increase of serum corticosterone and IL-1β, as well as higher levels of NLRP3 protein in hippocampus in the chronic stress-induced depression mice models." (PMID 35496273, 2022). "Our findings implied that NLRP3 may be a potential therapeutic target for depression and Sal can improve depressive symptoms by inhibiting the NLRP3-mediated pyroptosis." (PMID 35496273, 2022). "At present, while targeting NLRP3-dependent pyroptosis to treat depression is emphasized, it is also important to note that appropriate inflammasome activation-induced inflammation may be beneficial for neuro-environmental homeostasis." (PMID 35722622, 2022). "Autophagy and NLRP3 are potential targets for the treatment of depression." (PMID 34079796, 2021).